NOTCH2 (notch receptor 2)
Diseases named in the same sentence as NOTCH2 in open-access papers (continued):
Sharing a sentence is not in itself a finding about the gene and the disease.
pancreatic cancer (continued). "Similar to what was described in pancreatic cancer, Midkine-mediated upregulation of Notch1, responsible for Notch2 upregulation, was also reported as a resistance mechanism for biliary tract cancer." (PMID 34680255, 2021). "Several miRNAs can furthermore control the Notch pathway, e.g., miR34a and miR326 have been shown to target both Notch1 and Notch2 in gliomas and pancreatic cancer, and Notch3 3′ UTR can be targeted by miR206." (PMID 29462871, 2018). "Cell lines derived from melanoma (518A2), hepatocellular carcinoma (SNU398, HCC-3, Hep3B), and pancreas carcinoma (PANC1) express high amounts of nuclear NOTCH2." (PMID 28736522, 2017). "Notch2+ human pancreatic cancer Bxpc-3 and Panc-1 cells have properties of CSCs, which have a strong tumourigenic ability." (PMID 27917123, 2016). "Studies showed that Notch2+ cells in human pancreatic cancer Bxpc-3 and Panc-1 cells have the properties of cancer stem cells, with strong tumourigenic ability." (PMID 26464794, 2015). "Notch2 is a member of the notch family, and it is used to isolate, identify and localise pancreatic cancer stem-like cells." (PMID 26464794, 2015). "This analysis demonstrated significantly higher expression of NOTCH2 in pancreatic cancer." (PMID 41200204, 2025). "High-throughput approaches such as chromatin immunoprecipitation sequencing (ChIP-seq) have demonstrated that NOTCH1 and NOTCH2 exhibit distinct chromatin binding profiles in pancreatic cancer cell lines (e.g., BXPC3), suggesting functional divergence and target gene specificity." (PMID 41200204, 2025). "Furthermore, we investigated the role of NOTCH2 in pancreatic cancer in terms of immune infiltration, prognostic significance, somatic mutation profiles, and drug sensitivity." (PMID 41200204, 2025). "NOTCH2 may promote pancreatic cancer progression by suppressing ferroptosis, highlighting it as a potential therapeutic target." (PMID 41200204, 2025). "Therefore, NOTCH2 is a potential regulator of ferroptosis and redox homeostasis in pancreatic cancer." (PMID 41200204, 2025). "Preliminary evidence suggests that NOTCH2 may contribute to the malignant progression of pancreatic cancer by regulating ferroptosis and promoting an immunosuppressive tumor microenvironment." (PMID 41200204, 2025). "In this study, NOTCH2 was identified as a potential biomarker for pancreatic cancer." (PMID 41200204, 2025). "However, further experimental studies are still required to confirm the direct regulatory role of NOTCH2 in pancreatic cancer." (PMID 41200204, 2025). "Our findings suggest that NOTCH2 may serve as a novel biomarker and a potential therapeutic target in pancreatic cancer, offering new avenues for personalized anti-tumor strategies." (PMID 41200204, 2025). "Notch2 is also highly upregulated in pancreatic cancer-stem cells." (PMID 30285832, 2018). "Therefore, NOTCH2 may represent a crucial node in the M2 polarization regulatory network, yet its specific downstream signaling mechanisms in pancreatic cancer require further investigation." (PMID 41200204, 2025). "However, in pancreatic cancer, patients with high Notch2 expression have a worse prognosis." (PMID 33854967, 2021). "However, cytoplasmic staining of Jag1 and nuclear staining of Notch2 were observed at the same location of consecutive sections, suggesting that Jag1 may activate Notch2 during Kras-initiated pancreatic cancer development." (PMID 33268505, 2021). "It has been found that NOTCH2 and JAGGED1 are significantly upregulated in gemcitabine-resistant pancreatic cancer cells." (PMID 40830621, 2025). "Given the multiple pro-cancer roles of NOTCH2 in the initiation, progression, maintenance of CSC properties, and chemoresistance of pancreatic cancer, NOTCH2 represented an attractive potential therapeutic target." (PMID 41200204, 2025). "In pancreatic cancer cells with in vitro-induced GEM resistance (GR cells), NOTCH2 and its ligand Jagged-1 are significantly upregulated." (PMID 41200204, 2025).
pancreatic cancer (continued). "For example, MDK-Notch signaling, Notch2 as a functional receptor of MDK, regulates the epithelial-mesenchymal transition and chemotherapy resistance in pancreatic cancer and promotes the development of neuroblastoma." (PMID 34977035, 2021). "KMC14 cells expressed mRNA of Notch-1, Notch-2, Jagged-1, c-Met, CXCR-4, CD24 and CD44, except Jagged-2, that were reported as pancreatic cancer markers." (PMID 24278411, 2013). "Additionally, the restoration of miR-34 in human pancreatic cancer BxPC3 and MiaPaCa2 cells induces apoptosis and enhances sensitivity to GEM by inhibiting the expression of Notch1, Notch2, and Bcl-2." (PMID 38139352, 2023). "Tarextumab (OMP-59R5), a monoclonal antibody (mAb) against Notch2 and Notch3, has shown promising antitumor activity in several in vitro and in vivo models of SCLC, breast, ovarian, and pancreatic cancer that correlated with downregulation of Notch target genes." (PMID 34680255, 2021). "Moreover, a cross-reactive human monoclonal Notch2 and Notch3 antagonist, OMP-59R5 (Tarextumab), is effective in reducing cancer cell proliferation and the growth of breast, lung, ovarian, and pancreatic cancers." (PMID 29462871, 2018). "Additionally, NOTCH2 inhibitors RO4929097 and MK0752 are currently in trial for pancreatic cancer." (PMID 39456581, 2024). "Also, the pancreatic cancer dataset in TCGA indicates that DLL4, NOTCH1, NOTCH2, and NOTCH3 levels do not affect survival." (PMID 35673567, 2022).
lung carcinoma (30 papers, 2010 to 2025). "Six homeobox 1 (SIX1) and Notch receptor 2 (NOTCH2) protein expressions have been associated with invasive lung cancer, by inducing EMT and thus promoting advanced malignant phenotypes." (PMID 35444536, 2022). "Moreover, patients with high miR-296 expression had high OS and DFS, suggesting that AGAP2-AS1, miR-296, and NOTCH2 are associated with the prognosis of lung cancer patients." (PMID 33972506, 2021). "M2 macrophage-derived exosomes enriched lncRNA such as AGAP2/AS1 enhances radiotherapy immunity against lung cancer via elevating Neurogenic locus notch homolog protein 2 (NOTCH2) and reducing miR-296." (PMID 38188673, 2023). "Here, we found that Gsk3b, Notch2, Pik3cb, Myc, Cdkn1a, and Smad3 were increased in human lung cancer tissue and Cd‐transformed cells, while Pik3cb, Myc, Cdkn1a, and Smad3 were negatively correlated with circCIMT." (PMID 36814305, 2023). "Exosomal AGAP2-AS1 from M2 macrophages strengthens radiation resistance and cell cytotoxicity mediated by NK cells via suppressing miR-296 and elevating Notch2 in lung cancer." (PMID 36979471, 2023). "This study indicated that CAFs are collaborators with lung cancer cells in VM formation by Notch2 and Jagged1 interaction." (PMID 34485133, 2021). "In a word, we clarified that exosomal AGAP2-AS1 promotes the immunologic function of lung cancer patients after radiotherapy via down-regulating miR-296 and upregulating NOTCH2." (PMID 33972506, 2021). "First, AGAP2-AS1, miR-296, and NOTCH2 levels in lung cancer tissues and adjacent tissues were determined by reverse transcription-quantitative polymerase chain reaction (RT-qPCR)." (PMID 33972506, 2021). "M2 macrophage-derived exosomal AGAP2-AS1 enhances radiotherapy immunity in lung cancer by reducing miR-296 and elevating NOTCH2." (PMID 33972506, 2021). "M2-EVs have also been found to upregulate AGAP2-AS1 and NOTCH2 expression and downregulate miR-296 expression to strengthen the radioresistance of lung cancer cells." (PMID 34975877, 2021). "To identify the roles of AGAP2-AS1, miR-296, and NOTCH2 in radioresistance in lung cancer, we divided lung cancer patients into the radioresistant group and radiosensitive group." (PMID 33972506, 2021). "High-level Notch2 and Jagged1 expression was detected in two lung cancer cell lines and their CAFs, respectively." (PMID 34485133, 2021). "Expression of AGAP2-AS1, miR-296, and NOTCH2 in lung cancer cells and tissues from radiosensitive and radioresistant patients was determined, and the predictive role of AGAP2-AS1 in the prognosis of patients was identified." (PMID 33972506, 2021). "AGAP2-AS1 and NOTCH2 increased while miR-296 decreased in radioresistant patients and lung cancer cells." (PMID 33972506, 2021). "We aimed to identify the effect of the lncRNA AGAP2 antisense RNA 1 (AGAP2-AS1)/miR-296/notch homolog protein 2 (NOTCH2) axis on the progression and radioresistance of lung cancer." (PMID 33972506, 2021). "It has been demonstrated that the balance of the expression of NOTCH1 and NOTCH2 affected the biological behaviors of lung cancer cells." (PMID 33972506, 2021). "Notch2–Jagged1 cell–cell contact between cancer cells and CAFs contributes to the formation of VM networks, supported by Notch intracellular domain (NICD) 2 nuclear translocation and N2ICD target gene upregulated in lung cancer cells mixed with CAFs." (PMID 34485133, 2021). "Previous reports showed that Notch2 or Notch3 are involved in gastric carcinogenesis or lung cancer progression." (PMID 26416455, 2015). "For instance, during the development of non-small cell lung cancer, Notch2 mediated cell differentiation, whereas Notch1 promoted the initiation and development of lung cancer." (PMID 26563263, 2015).
lung carcinoma (continued). "Outcomes of cellular and animal experiments in our study suggested that macrophage-derived exosomes, exosomal AGAP2-AS1, and downregulated miR-296 promoted malignant behaviors and resistance to NK-cells mediated cytotoxicity of lung cancer cells via regulation of NOTCH2." (PMID 33972506, 2021). "In contrast to Notch1 and Notch3, which are regarded as oncogenic factors responsible for lung cancer development, whether Notch2 has similar roles should be further investigated." (PMID 34485133, 2021). "γ-secretase inhibitors can successfully block Notch2–Jagged1 interaction to prevent VM formation, thus providing new avenues for using this strategy as adjuvants to improve the efficiency or resistance of antiangiogenic therapies for lung cancer." (PMID 34485133, 2021). "miR-181b-mediated replacement therapy may therefore represent a promising compensator in chemoresistance, and modulating the miR-181b/Notch2 signalling pathway may be an efficient therapeutic strategy for lung cancer." (PMID 30470250, 2018). "PNO1/CRISPR/Cas9 inhibited the expression of Notch1, Notch2, Notch3 Jagged1, and DLL1 in lung cancer A549 and H460 cells." (PMID 36625087, 2023). "The results indicated that AGAP2-AS1, miR-296, and NOTCH2 expression levels were related to the tumor, node, and metastasis (TNM) stage and lymph node metastasis (LNM) of lung cancer patients." (PMID 33972506, 2021). "We concluded that CAFs induce lung cancer to form capillary-like structures, which may provide an intravasation or extravasation channel for cancer cells and tumor-promoting neutrophils, and alter the cancer ability to form VM networks by direct Notch2–Jagged1-mediated contact." (PMID 34485133, 2021). "Studies have demonstrated that Notch2 contributes to the increase of cancer stem cell properties and impairment of CD8+ T cell anticancer activity in patients with lung cancer." (PMID 34485133, 2021). "Kaplan–Meier method was conducted to analyze the relationships of AGAP2-AS1, miR-296, and NOTCH2 levels with the OS and DFS of lung cancer patients." (PMID 33972506, 2021). "To determine the efficacy of Notch2-shRNA in reducing the intracellular levels of Notch2, we treated A549 (lung cancer) and SSK-41 cells (B-cell lymphoma) with viral supernatants of two different shRNA constructs in a lentiviral vector targeting Notch2." (PMID 33400727, 2020). "Researchers discovered that in lung cancer, NEDD4L increased Notch2 ubiquitination and degradation." (PMID 39717922, 2025). "It was implied that NOTCH2 could be used as a downstream target of AGAP2-AS1 and miR-296 in radioresistant lung cancer cells." (PMID 33972506, 2021). "The crosstalk of cancer cells and CAFs by Notch2 and Jagged1 in the TME studied here confirms that γ-secretase inhibitors could be a promising strategy for improving anti-VEGF antibody treatment in lung cancer." (PMID 34485133, 2021). "By contrast, inhibition of Notch2–Jagged1 interaction reduced VM formation and cancer growth in vivo, indicating that VM networks made by CAFs and cancer cells provide a beneficial TME for lung cancer." (PMID 34485133, 2021). "Besides, in lung cancer, lncRNA AGAP2-AS1 enhanced radioresistance through miR-296/NOTCH2 axis." (PMID 35600868, 2022). "We conducted this research to identify the roles of M2 macrophage-derived exosomal AGAP2-AS1 in the development of lung cancer, and we found that exosomal AGAP2-AS1 promoted radiotherapy immunity of lung cancer patients after radiotherapy by downregulating miR-296 and overexpressing NOTCH2." (PMID 33972506, 2021).
Hajdu-Cheney syndrome (27 papers, 2012 to 2026). "Hajdu-Cheney syndrome (HCS) is a rare genetic skeletal disorder caused by truncating variants of NOTCH2, characterized by progressive bone resorption and marked phenotypic heterogeneity." (PMID 42123373, 2026). "Prenatal testing is possible, and is advised to be carried out in families with Hajdu-Cheney syndrome, testing for chromosome 1p12 exon 34 mutations in the NOTCH2 gene." (PMID 41007038, 2025). "Hajdu-Cheney syndrome (HCS) is a rare autosomal dominant condition caused by a pathogenic variant in the NOTCH2 gene." (PMID 40235644, 2025). "Hajdu-Cheney syndrome (HCS) is a rare autosomal dominant manifestation of a congenital genetic disorder caused by a mutation in the NOTCH2 gene." (PMID 36232677, 2022). "In summary, the NOTCH2 mutation that causes Hajdu-Cheney syndrome is a nonsense mutation that replaces a stop codon through a base swap, leading to translation of the transcribed messenger RNA beyond the original gene sequence after the mutation." (PMID 36232677, 2022). "Hajdu-Cheney syndrome is a genetic disease and is related to the mutation of the NOTCH2 gene on chromosome 1 (locus 1p13-p11)." (PMID 34501688, 2021). "Previous human genetic studies on the NOTCH2 gene have revealed that heterozygous truncating mutations in exon 34 cause Hajdu-Cheney syndrome, which is characterized by progressive focal bone destruction, including acro-osteolysis and generalized osteoporosis." (PMID 32312275, 2020). "NOTCH2 mutations are associated with Allagile Syndrome and Hajdu-Cheney syndrome, two autosomal dominant conditions." (PMID 26179878, 2015). "Recently it was shown that Hajdu-Cheney syndrome, a rare skeletal disorder, is caused by heterozygous mutations clustering to the last exon of the NOTCH 2 gene, which code for a truncated protein that acts in a gain-of-function manner." (PMID 24725993, 2014). "Mutations in NOTCH2 can also cause the Hajdu-Cheney syndrome, a disorder of severe and progressive bone loss." (PMID 23597238, 2013). "Alternate approaches to downregulate specific Notch receptors have included ASOs, and we demonstrated that Notch2 ASOs downregulate Notch2 expression in vitro and in vivo and ameliorate the osteopenia of mice harboring a Notch2 mutation replicating the one found in Hajdu Cheney Syndrome." (PMID 35536858, 2022). "The best known is the Hajdu-Cheney syndrome linked to a NOTCH2 mutation." (PMID 35908058, 2022). "In 2012, a Japanese group reported that one girl with Hajdu-Cheney syndrome developed premature ovarian failure, indicating that alteration in the NOTCH2 gene may be also associated with premature ovarian failure." (PMID 32312275, 2020). "Hajdu-Cheney syndrome is an autosomal dominant skeletal disorder characterized by facial anomalies, osteoporosis, and acro-osteolysis caused by truncating mutations in the last exon of Notch2." (PMID 27855169, 2016). "Although Hajdu-Cheney Syndrome (HCS) was first described in 1948, the identification of its associated NOTCH2 gene mutation was only reported in the last decade." (PMID 40235644, 2025). "Hajdu-Cheney-Syndrome (HCS), caused by gain-of-function mutations in the Notch2 gene, is a rare inherited disease featuring early-onset osteoporosis and increased risk for fractures and non-union." (PMID 37452111, 2023). "Mutations of NOTCH2 cause the deletion of the PEST domain in the NICD, which results in NOTCH2 overexpression, leading to the Hajdu-Cheney syndrome." (PMID 36232677, 2022). "Serpentine fibula-polycystic kidney syndrome (SFPKS) is allelic to HCS and commonly associated with missense NOTCH2 mutations." (PMID 30420927, 2018). "The clinical and radiographic examination initially directed diagnosis towards a Hajdu-Cheney syndrome, soon discarded owing to the presence of long-bone lesions and the absence of NOTCH2 mutation." (PMID 35908058, 2022).
Hajdu-Cheney syndrome (continued). "Hajdu-Cheney syndrome, which is driven by the production of a stabilized NOTCH2 lacking a functional PEST (peptide sequence that is rich in proline (P), glutamic acid (E), serine (S), and threonine (T)) degradation domain, is caused by gain-of-function mutations in NOTCH2." (PMID 34039391, 2021). "Thus we rule out Hajdu-Cheney syndrome caused by NOTCH2 exon 34 mutation." (PMID 26380986, 2015). "The pathogenic variants associated with LMS are analogous to those reported in Hajdu Cheney Syndrome (HCS), a genetic disorder caused by pathogenic variants in exon 34 of NOTCH2 resulting in the translation of a truncated NOTCH2 protein lacking the PEST domain and a gain-of-NOTCH2 function." (PMID 33519922, 2020).